PRKN (parkin RBR E3 ubiquitin protein ligase)
Diseases named in the same sentence as PRKN in open-access papers (continued):
Sharing a sentence is not in itself a finding about the gene and the disease.
Parkinson disease (continued). "Inherited mutations in PRKN are the most common cause of autosomal recessive juvenile form of Parkinson’s disease, thus emphasizing the neuroprotective importance of PRKN." (PMID 34354738, 2021). "Mutations in PINK1 or the Parkin-encoding gene PRKN are associated with autosomal recessive, early-onset forms of Parkinson’s disease (PD)." (PMID 34228161, 2021). "In three brains from subjects with non-PRKN-linked parkinsonism, the levels of H2O2 were similar to those measured in age-matched controls." (PMID 33694021, 2021). "Among AR parkinsonisms, forms caused by biallelic pathogenic variants in the PRKN, PINK1, and DJ-1 genes are thus far considered pure forms of EOPD." (PMID 34630269, 2021). "Biallelic pathogenic variants in the PRKN gene are the most common cause of early-onset Parkinson's disease." (PMID 34514401, 2021). "PRKN is the most common gene responsible for early-onset Parkinson's disease (EOPD), while rare variants of PLA2G6 likely raise PD susceptibility in the Chinese population." (PMID 33154736, 2020). "It is also reported that a Chinese EOPD patient carrying a heterozygous mutation c.1321T>C of PRKN appeared to have symmetrical parkinsonism at onset." (PMID 33154736, 2020). "In another example, somatic depletion of PRKN, a component of a multiprotein E3 ubiquitin ligase complex, and a known gene associated with Parkinson’s disease, was also reported in ovarian and lung cancers." (PMID 32371905, 2020). "Polymorphic variants in the PRKN gene were initially associated with the autosomal recessive form of Parkinson's disease (AR-JP)." (PMID 32433683, 2020). "PRKN mutations were present in 20% (3/15, 95% CI 7.0–45.2%) of young-onset patients with two additional family members affected by Parkinson’s disease." (PMID 31324919, 2019). "Earlier biochemical and genetic studies revealed that PINK1, which has been associated to Parkinson's disease, works together with PRKN (also known as parkin) in the pathway involved in mitochondrial quality control." (PMID 31515286, 2019). "The PRKN mutation in Parkinson disease showed a good response to STN DBS, with substantial improvement of motor complications and a relatively low prevalence of dementia up to 4 years after surgical treatment." (PMID 30707228, 2019). "This study suggests that LRRK2, GBA, and PRKN mutations in Parkinson disease are associated with motor improvements after STN DBS, comparable to idiopathic Parkinson disease." (PMID 30707228, 2019). "The autosomal recessive forms of Parkinson’s disease are caused by mutations of Parkin RBR E3 ubiquitin protein ligase (PARK2) and PTEN-induced putative kinase 1 (PINK1), which regulates degradation of damaged mitochondria (mitophagy)." (PMID 30744021, 2019). "Previous studies reported alterations of mitochondrial function in fibroblasts from patients with PRKN mutation-associated Parkinson’s disease (PRKN-PD) but have been only conducted in glycolytic conditions, potentially masking mitochondrial alterations." (PMID 31180333, 2019). "Alteration of mitophagy efficiency due, for example, to genetic mutations of key genes, such as PINK1 or PRKN (PARKIN), has been associated with neurological disorders (e.g., Parkinson disease, cancer, heart failure, and aging)." (PMID 30728463, 2019). "Early‐onset Parkinson's disease (PD) is the most common inherited form of parkinsonism, with the PRKN gene being the most frequently identified mutated." (PMID 30328284, 2018). "One such example is the well-established genetic and functional interaction between PTEN-induced putative (mitochondrial) kinase 1 (PINK1) and the E3 ubiquitin ligase parkin (PRKN), two genes mutated in Parkinson's disease." (PMID 21829392, 2011). "DJ-1 gene, PTEN-induced putative kinase 1 (PINK1) gene and parkin (PRKN) gene mutations are responsible for autosomal recessive Parkinson cases." (PMID 19399218, 2009).
Parkinson disease (continued). "When evaluating the 16 previously published carriers of a homozygous deletion of Exon 2 from the International Parkinson's Disease and Movement Disorder Society Gene Database (MDSGene) database, the median age at onset is later (39.5 years) than in carriers of other PRKN pathogenic variants." (PMID 41724727, 2026). "We expressed GEM-SCOPe in differentiated astrocytes and neurons from a human pluripotent stem cell PRKN-knockout model of Parkinson’s disease and identified disease-associated changes in proliferation, lysosomal distribution, mitochondrial transport and turnover, and reactive oxygen species." (PMID 38979135, 2025). "Biallelic mutations in the PRKN gene are a common cause of early‐onset Parkinson's disease (EOPD)." (PMID 40884420, 2025). "Additionally, some familial forms of Parkinson's disease have been linked to loss-of-function mutations in PINK1 or PRKN in humans, and genetic knockout of Pink1 or Prkn expression in mice results in central nervous system defects (49, –51)." (PMID 39928869, 2025). "Biallelic LOF mutations in PRKN causes early onset Parkinson’s disease (PD)." (PMID 40894167, 2025). "There is a genetic component to the disease, which accounts for between 10 and 15% of cases, with several individual genes (such as LRRK2, SNCA, PINK1, PARK7 and PRKN) associated with Parkinson’s disease and over 90 gene loci that can increase the risk of developing Parkinson’s disease." (PMID 38276234, 2024). "Complete loss of PINK1 or PRKN function unequivocally leads to early-onset Parkinson disease, but it is debated whether impairments in mitophagy contribute to disease later in life." (PMID 38041584, 2024). "However, the study identified a patient with both SCZ and early‐onset Parkinson's disease who carries biallelic pathogenic CNVs in PRKN." (PMID 37915257, 2024). "We suspect that in the case of the 57-year-old male admitted due to meningitis, the harbored ~176 kb tandem duplication of chr 6 (the coding exon 2 of the PRKN gene) may have predisposed this patient to Parkinson-like symptoms." (PMID 36671517, 2023). "Thus, inhibition of USP30 represents an actionable target to correct pathologies associated with PINK1 or PRKN defects, such as Parkinson disease or pulmonary fibrosis." (PMID 34844982, 2022). "In dopaminergic neurons, generated from Parkinson disease patients carrying loss of function PRKN mutations, compound 39 could significantly restore mitophagy to a level approaching control values." (PMID 34844982, 2022). "Mutations of PRKN are associated with hereditary Parkinson’s disease." (PMID 35706047, 2022). "The loss of these complementary redox effects may augment oxidative stress during ageing in dopamine-producing cells of mutant PRKN allele carriers, thereby enhancing the risk of Parkinson’s-linked neurodegeneration." (PMID 33694021, 2021). "Mutations in PRKN are the most common cause of early onset Parkinson’s disease." (PMID 32968089, 2020). "Additionally, two mutations in the Parkin protein (encoded by the PRKN/PARK2 gene), which has been linked to Parkinson’s disease, increase its predicted aggregation propensity." (PMID 31914925, 2020). "Genetic screening for LRRK2, GBA, and PRKN mutations in patients with Parkinson disease who are candidates for subthalamic deep brain stimulation may serve to inform outcomes." (PMID 30707228, 2019). "Loss-of-function mutations in the PINK1 and PRKN genes are the most common cause of early-onset Parkinson disease (PD)." (PMID 40624741, 2025). "However, isolated generalised dystonia is very uncommon in PRKN pathogenic variant carriers, suggesting shared and sometimes convergent mechanisms in different movement disorders, particularly ataxia, dystonia and parkinsonism." (PMID 38458754, 2024). "As such, complete loss of either enzyme, PINK1 or PRKN, is invariably linked to early-onset Parkinson disease (PD)." (PMID 36469690, 2023).
Parkinson disease (continued). "While loss of either PINK1 or PRKN is genetically linked to Parkinson disease (PD) and activating the pathway seems to have great therapeutic potential, there is no formal proof that stimulation of mitophagy is always beneficial." (PMID 36469690, 2023). "PINK1 (PTEN induced kinase 1) and PRKN-mediated mitophagy is an important mitochondrial quality control pathway which selectively degrades damaged mitochondria and is tightly associated with neurodegenerative diseases, including Parkinson disease and amyotrophic lateral sclerosis." (PMID 40395318, 2023). "Of note, PINK1 and PRKN are mutated in autosomal recessive Parkinson disease (PD) and their roles in mitophagy indicate the connection between mitophagy and PD, which will be discussed in detail in the following sections." (PMID 34829881, 2021). "Eight loci-PRKN, SNCA, GBA1, LRRK2, APOE, MTHFR, SYT11, and NR4A2-emerged as recurrently associated with Parkinson's disease." (PMID 41798285, 2026). "Defective mitochondrial quality control in response to loss of mitochondrial membrane polarization is implicated in Parkinson’s disease by mutations in PINK1 and PRKN." (PMID 40196634, 2025). "Familial Parkinson's disease cases, which account for approximately 5%–10% of all cases, are associated with mutations in genes such as SNCA, LRRK2, PINK1, and PRKN." (PMID 40808332, 2025). "PRKN accounts for 1% of all adult onset and 4.6% to 10.5% of early onset Parkinson disease cases; it has a median age at onset of 31 years and a slowly progressive clinical course." (PMID 38840441, 2025). "Network graph analyses identified the PRKN gene as a key player across multiple identified brain regions, reinforcing the connection between Major Depression and Parkinson’s disease." (PMID 40559334, 2025). "In all three cases, WGS identified CNVs and confirmed zygosity and pathogenicity, resulting in genetic diagnoses of PRKN‐related Parkinson disease, TAOK1‐related neurodevelopmental disorder, and AP1G1‐related Usmani‐Riazuddin syndrome." (PMID 38840441, 2025). "Parkinson’s disease, where the Parkin name comes from, is associated with mutations in either PINK1 or PRKN." (PMID 40243689, 2025). "PD risk genes such as DJ-1, PINK1, PRKN, and LRRK2 share mitochondrial dysfunction, and 1-methyl-4-phenyl-1,2,3,6-tetrahydropyridine, a complex I inhibitor, induces parkinsonism, which is frequently used in PD mouse models." (PMID 40149582, 2025). "Defective mitochondrial quality control is linked to Parkinson’s disease via mutations in the genes PINK1 and PRKN." (PMID 40743392, 2025). "This allowed reclassification of the variant to likely pathogenic, confirming the genetic diagnosis of autosomal recessive PRKN‐related Parkinson disease." (PMID 38840441, 2025). "The clinical phenotype is similar to the disease in PRKN carriers and is characterized by early-onset parkinsonism, effective response to levodopa, slow disease progression, and occasional dystonia." (PMID 40722695, 2025). "In our series, WGS analysis enabled diagnosis of PRKN‐related Parkinson disease, TAOK1‐related neurodevelopmental disorder, and Usmani‐Riazuddin syndrome, which had significant implications for the clinical care of the patients and families concerned." (PMID 38840441, 2025). "In neurodegenerative diseases, notably, frontotemporal dementia (FTD) and Parkinson’s disease (PD), genetic mutations—including MAPT, LRRK2, PINK1, PRKN, and SNCA—have been reported to alter Nrf2 signaling, both in vitro and in vivo." (PMID 41154499, 2025). "In a Central Asian study of an early-onset Parkinson’s disease population in Kazakhstan, pathogenic mutations were found in only 6% of cases and only in the LRRK2 and PRKN genes, confirming regional differences between populations." (PMID 38397244, 2024). "For instance, mutations in PRKN and PINK1 are often evident in patients with familial and sporadic Parkinson’s disease (PD)." (PMID 38678018, 2024).
Parkinson disease (continued). "Those in the LRRK2 and PRKN compound heterozygous/homozygous groups were more likely to have a first-degree relative with Parkinson’s disease (40%, 47% versus 19%; P = 1.11 × 10−11 and 1.36 × 10−6)." (PMID 39074992, 2024). "Mitochondrial dysfunction is a key aspect of Parkinson’s disease, and mutations in the PRKN/PARK2 gene have been reported to be associated with early-onset familial PD." (PMID 37483347, 2023). "Examples of RBR E3 ligases are Parkin (PRKN), involved in Parkinson’s disease, and HOIP, a member of the linear ubiquitin chain assembly complex (LUBAC), responsible for assembling M1-linked linear Ub chains." (PMID 36926679, 2023). "Mutations in the PRKN and PINK1 genes account for most of the recessive early-onset Parkinson’s disease (PD) cases." (PMID 36941054, 2023). "This is parsimonious with a gut-linked early pathophysiology of Parkinson’s disease as well as with mutations in the PINK1 and PRKN ubiquitin ligase genes as risk factors for an early-onset form of Parkinson’s disease." (PMID 37174637, 2023). "Patients with PRKN or PINK1 also manifested the juvenile- (under 20 years of age at onset) or young-onset parkinsonism (under 40 years) with excellent response to even the low doses of levodopa, which leads to the brain pathology in the absence of LBs." (PMID 35720097, 2022). "The clinical phenotype resembles PRKN-related PD with typical slow-progressive parkinsonism with good and persistent response to Levodopa and low prevalence of non-motor symptoms." (PMID 36291241, 2022). "The genetic variation of PRKN is closely related to the pathogenesis of Parkinson’s disease, mainly manifested in mitochondrial dysfunction." (PMID 36072790, 2022). "We observed a similar pattern in a mitophagy-defective worm model of Parkinson’s disease in which there is a deletion of pdr-1/PRKN." (PMID 34948242, 2021). "Mutations of three genes, PRKN, PINK1, and DJ-1 cause pure phenotypes usually characterized by levodopa-responsive Parkinson's disease." (PMID 33841314, 2021). "Biallelic pathogenic variants in PRKN (PARK2), encoding the E3 ubiquitin ligase parkin, lead to early-onset Parkinson's disease." (PMID 34514401, 2021). "Apart from α-Synuclein accumulation, Parkinson’s pathology can also be attributed to mutations in genes such as PINK1 (PTEN-induced putative kinase 1), DJ-1, PRKN (parkin) and LRRK2 (leucine-rich repeat kinase 2)." (PMID 34830158, 2021). "Biallelic pathogenic variants in PRKN (Parkin, MIM*602544), are the most common genetic cause of early-onset pure Parkinsonism (PARK2, MIM#602544)." (PMID 34630269, 2021). "Relevant Parkinson’s Disease (PD)-associated genes PARK7, PINK1, SNCA, and PRKN are expressed at medium-to-high levels, while LRRK2 is expressed at overall lower levels." (PMID 33281596, 2020). "PRKN is fundamental in various neurodegenerative diseases, including Parkinson’s disease, Alzheimer’s disease, Amyotrophic Lateral Sclerosis and Huntington’s disease." (PMID 31948106, 2020). "This implicates KMO in mitochondrial quality control mechanisms which are regulated in part by the familial Parkinson’s disease (PD) associated proteins PINK1 and PRKN." (PMID 33170836, 2020). "Here, we describe in vitro evaluation of antisense oligomers that restore functional parkin expression in cells derived from a Parkinson’s patient carrying a heterozygous PRKN exon 3 deletion, by inducing exon 4 skipping to correct the reading frame." (PMID 33019779, 2020). "Although the effects of mutations of the PRKN and PINK1 genes on patients with Parkinson's disease have been extensively studied, mutations of these genes in Vietnamese PD have not yet been investigated." (PMID 32856414, 2020). "Rare deletions extending in the neighboring PRKN coregulated gene (PACRG) result in the same early onset parkinsonism phenotype." (PMID 31551675, 2019).
Parkinson disease (continued). "This meta-analysis and systematic review suggests that patients with Parkinson disease who are carriers of LRRK2, GBA, and PRKN gene mutations show good motor advantages after STN DBS, comparable to patients with idiopathic Parkinson disease." (PMID 30707228, 2019). "On the other hand, mutations in the recessive genes including parkin (PRKN), PTEN-induced putative kinase 1 (PINK1) and DJ-1 are causative of early-onset parkinsonism shearing largely identical clinical phenotypes, but distinct neuropathology." (PMID 30618654, 2018). "Mutations in the genes PRKN and LRRK2 are the most frequent known genetic lesions among Parkinson's disease patients." (PMID 18211709, 2008). "In addition, the protein products of two genes linked to recessive Parkinson disease (PD), PINK1 (PTEN induced kinase 1) and PRKN (parkin RBR E3 ubiquitin protein ligase), mediate the ubiquitination of depolarized mitochondria for clearance." (PMID 41277110, 2026). "The genetic diagnosis of PRKN‐related Parkinson disease was consistent with the clinical presentation and family history, and facilitated accurate genetic counselling for the patient in relation to prognosis and risks to wider family members, including children and siblings." (PMID 38840441, 2025). "Approximately 5–10% of patients, however, develop a “monogenic form of Parkinson’s Disease”, which is caused by pathogenic variants in SNCA, LRRK2, and VPS35, genes exhibiting autosomal dominant inheritance, along with PRKN, PINK1, and DJ-1, genes which follow autosomal recessive inheritance." (PMID 40564955, 2025). "Variants in seven genes (LRRK2, GBA1, PRKN, SNCA, PINK1, PARK7 and VPS35) have been formally adjudicated as causal contributors to Parkinson’s disease; however, individuals with Parkinson’s disease are often unaware of their genetic status since clinical testing is infrequently offered." (PMID 39074992, 2024). "A role of PRKN in immune modulation and enhanced T cell effector functions carries important implications for the pathogenesis of cancer and other conditions, including the response to infectious pathogens and Parkinson’s Disease." (PMID 39213189, 2024). "The absence of Parkinson's symptoms in 10 other monoallelic carriers of the same pathogenic CNV further reflects the lack of effect of monoallelic pathogenic variants in PRKN in the absence of a second hit." (PMID 37915257, 2024). "PRKN is a key gene involved in mitophagy in Parkinson’s disease." (PMID 38424181, 2024). "Furthermore, a large-scale study is currently underway in the United States, which aims to determine the frequency of variants in the seven most common genes associated with Parkinson’s disease: GBA, LRRK2, PRKN, SNCA, PINK1, PARK7, and VPS35." (PMID 38397244, 2024). "CNVs were detected affecting genes where deletions or duplications are established as a common mechanism, like PRKN (in Parkinson’s disease), DMD (in Duchenne muscular dystrophy) and PMP22 (in neuropathies), but also genes in which no intragenic CNVs have been reported to date." (PMID 36781956, 2023). "Interestingly we found associations that approach GWS for total tauTBS (P = 8.03E-07) and total tauTX (P = 9.48E-06) with rs117691004 which is located in the PRKN gene known to play a role in Parkinson’s Disease." (PMID 36609403, 2023). "Examples of CNVs that have been proven to cause neurodegenerative diseases include duplications of APP leading to EOAD, multiplications of alpha-synuclein (SNCA) causing forms of Parkinson’s disease (PD) and DLB, as well as both deletions and duplications of PRKN that are known to cause forms of PD." (PMID 34321086, 2021). "Unlike the case of PRKN/PARK2 and Parkinson’s disease, there is a paucity of data supporting the association between BNIP3L mutations and specific diseases." (PMID 34930907, 2021). "Specimens of three non-PRKN-linked patients with parkinsonism showed H2O2 levels comparable to those from age-matched normal cortices (red circles)." (PMID 33694021, 2021).